CTSK (cathepsin K)
Diseases named in the same sentence as CTSK in open-access papers (continued):
Sharing a sentence is not in itself a finding about the gene and the disease.
keratoconus (2 papers, 2022 to 2023). A degenerative, structural disorder of the eye, characterized by a cone-shaped protrusion of the cornea. "Further cyclical mechanical experiments revealed that several protease genes (including MMP1, MMP3, CTSD and CTSK) can be induced by stretch, indicating the inductive role of mechanical stretch in keratoconus pathogenesis." (PMID 35821117, 2022). "Consistent with the detected changes in mRNA levels, immunohistochemical analyses confirmed increased CTSD and CTSK protein levels in keratoconus stromal cells." (PMID 35821117, 2022). "Among these genes, two lysosomal cysteine proteases CTSD and CTSK were identified, providing potential biomarkers for keratoconus diagnosis." (PMID 35821117, 2022). "Importantly, the authors identified cathepsin D (CTSD), cathepsin K (CTSK), YES-associated protein 1 (YAP1), and TEA domain transcription factor (TEAD1) as novel biomarkers in keratoconus stromal cells." (PMID 37138096, 2023). "We then evaluated the subtype-specific expression of the keratoconus-related enzymes identified in this study, and found that CTSD was specifically and highly expressed in keratoconus across all subtypes, while CTSK was mainly differentially enriched in C0-C2 cells." (PMID 35821117, 2022). "Further cyclical mechanical experiments on human corneal stromal cell lines demonstrated that mechanical stretch prompted the expression of several protease genes, including MMP1, MMP3, CTSD and CTSK, implying the activating effect of mechanical stretch on proteases during keratoconus progression." (PMID 35821117, 2022). "In corneal stromal cells, we identified two novel keratoconus-related markers, namely cathepsin D (CTSD) and cathepsin K (CTSK)." (PMID 35821117, 2022).
knee osteoarthritis (2 papers, 2021 to 2023). "Pre-clinical findings have been translated to clinical trials with the selective cathepsin K inhibitor MIV-711 reducing bone and cartilage disease progression in individuals with symptomatic, radiographic knee osteoarthritis." (PMID 38144567, 2023).
lung adenocarcinoma (2 papers, 2018 to 2024). A carcinoma that arises from the lung and is characterized by the presence of malignant glandular epithelial cells. "Interestingly, high expression of CTSK was found in the desmoplastic reactive stroma of the lung adenocarcinoma, indicating that stromal production of CTSK can favor or modulate the invasion of tumor cells." (PMID 29618339, 2018). "We assess the effect of lung adenocarcinoma cells on TAM through detecting the expression of SHP2, p- STAT1, p-STAT3, p-STAT5, p-STAT6, IL-4, IL-10, Cathepsin-L, Cathepsin-S, Cathepsin-K and Arginase-1 in each group of THP1 cells cocultured with and without A549 cells by western blot." (PMID 38747738, 2024).
lysosomal disorder (2 papers, 2020 to 2025). "Mislocalized cathepsin K promotes cardiac disease in a zebrafish model of the lysosomal disorder mucolipidosis II and can be targeted by cathespin inhibition." (PMID 33055423, 2020). "Collectively, these data identify mislocalized cathepsin K as an initiator of cardiac disease in this lysosomal disorder and establish cathepsin inhibition as a viable therapeutic strategy." (PMID 33055423, 2020).
metastatic disease (2 papers, 2021 to 2023). "CTSK overexpression is associated with cancer metastatic disease with a potential prognostic value." (PMID 37198626, 2023). "The relationship between cathepsin K over-expression in the tumor microenvironment and tumor progression has been reported, and it is widely accepted that cathepsin K over-expression is associated with cancer metastatic disease with a potential prognostic value." (PMID 34069976, 2021).
non-small cell lung carcinoma (2 papers, 2020 to 2022). A group of at least three distinct histological types of lung cancer, including non-small cell squamous cell carcinoma, adenocarcinoma, and large cell carcinoma. "However, there is little information regarding the involvement of Cathepsin K in non-small cell lung cancer (NSCLC)." (PMID 32927648, 2020).
oral squamous cell carcinoma (2 papers, 2018 to 2025). "The aim of the study was to discover the clinicopathological and prognostic implications of cathepsin K (CTSK) expression in oral squamous cell carcinoma." (PMID 29618339, 2018).
pancreatic cancer (2 papers, 2023 to 2025). "The CCLE dataset revealed elevated expression of six module genes (GFPT2, MFAP5, CTSK, MMP2, FSTL1, and PRRX1) associated with poor overall survival in patients with pancreatic cancer." (PMID 40430018, 2025). "In conclusion, our study identified PLAU and CTSK as potential biomarkers for pancreatic cancer through bioinformatics analysis of microarray data." (PMID 38077303, 2023). "The expression of PLAU and CTSK was significantly higher in pancreatic cancer samples than in normal breast tissues (p < 0.001)." (PMID 38077303, 2023). "In conclusion, our study successfully identified a module of six key genes—GFPT2, MFAP5, CTSK, MMP2, FSTL1, and PRRX1—through Weighted Gene Co-expression Network Analysis (WGCNA) to assess cancer-associated fibroblast (CAF) infiltration in pancreatic cancer (PC)." (PMID 40430018, 2025). "This study is aimed at employing bioinformatics to investigate and comprehend the expression of PLAU and CTSK in pancreatic cancer, as well as their relationship with clinicopathological and prognostic significance, underlying molecular mechanisms, and immune cell infiltration, to aid physicians." (PMID 38077303, 2023). "In addition, the ROC curve showed that PLAU and CTSK had excellent predictive ability to distinguish pancreatic cancer, with an area under the curve of 0.968 (95% CI = 0.947-0.988) for CTSK and an area under the curve of 0.976 (95% CI = 0.961-0.991) for PLAU." (PMID 38077303, 2023). "Utilizing the CCLE database, it was confirmed that fibroblast cell lines exhibited elevated mRNA levels of the six module genes (GFPT2, MFAP5, CTSK, MMP2, FSTL1, and PRRX1) (accessed on 2 March 2025) compared to pancreatic cancer cell lines." (PMID 40430018, 2025). "Our findings contribute to the development of new therapeutic strategies for pancreatic cancer and lay the foundation for further studies to elucidate the role of PLAU and CTSK in this disease." (PMID 38077303, 2023). "Expression profiles and clinical data from the Cancer Genome Atlas (TCGA) were then used to compare the expression levels of CTSK and PLAU in pancreatic cancer and healthy pancreatic tissues via the Wilcoxon rank-sum test, with further validation using qPCR." (PMID 38077303, 2023). "The results showed that COL1A1, PLAU, and CTSK were highly expressed in the three datasets, with COL1A1 having been shown to play a significant role in pancreatic cancer." (PMID 38077303, 2023). "As COL1A1 has been well studied in pancreatic cancer, we selected PLAU and CTSK, which have shown reductions in overall and disease-free survival." (PMID 38077303, 2023). "The results demonstrated that CTSK and PLAU were overexpressed in pancreatic cancer and that the hypomethylation status of both genes was associated with a poor prognosis." (PMID 38077303, 2023). "To summarize, our findings suggest that CTSK and PLAU may serve as novel potential biomarkers for pancreatic cancer." (PMID 38077303, 2023). "However, the molecular mechanism and clinical prediction of CTSK in pancreatic cancer have not yet been studied." (PMID 38077303, 2023). "Consequently, CTSK and PLAU have potential as prognostic biomarkers for pancreatic cancer." (PMID 38077303, 2023). "As the molecular mechanism of CTSK and PLAU in the development of pancreatic cancer has not been studied, we identified the DEGs of these two genes in pancreatic cancer through the DsEq2 package and conducted functional studies of KEGG, GO, and GSEA enrichment." (PMID 38077303, 2023).
Parkinson disease (2 papers, 2011 to 2014). A progressive degenerative disorder of the central nervous system characterized by loss of dopamine producing neurons in the substantia nigra and the presence of Lewy bodies in the substantia nigra and locus coeruleus. "Transcripts for the lysosomal proteins hexosaminidase subunit A, aspartyl glucosaminidase, cathepsin K, SCARB2/LIMP2 and iduronidase alpha all rose significantly in control, Gaucher disease and Parkinson’s disease with GBA mutation cells after ambroxol treatment." (PMID 24574503, 2014).
psoriatic arthritis (2 papers, 2016 to 2023). Joint inflammation associated with psoriasis. "This retrospective case-control study examined the relationship between the serum and synovial levels of cathepsin G (CatG) and cathepsin K (CatK) in patients with psoriatic arthritis (PsA) and their association with disease activity." (PMID 37892071, 2023). "Psoriatic arthritis patients had lower osteocalcin, as well as higher C-telopeptide of type I collagen and cathepsin K serum levels compared with psoriasis vulgaris patients and controls." (PMID 27050092, 2016).
renal oncocytoma (2 papers, 2023 to 2024). "The findings revealed that Cathepsin K was positively expressed in both tumour types, with stronger staining observed in renal oncocytoma compared to the weaker, more membranous staining in ChRCC." (PMID 39684226, 2024). "In this morphological scenario, cathepsin-K (clone 3F9) is a useful tool for differentiating renal oncocytoma, chromophobe RCC, and LOT which are negative for cathepsin-K (clone 3F9), from ESC-RCC, EVT, and mTOR-mutated eosinophilic RCC which are positive for this marker." (PMID 37938323, 2023).
sarcoma (2 papers, 2012 to 2024). A usually aggressive malignant neoplasm of the soft tissue or bone. "Because cathepsin K is overexpressed in sarcomas, the cathepsin K-specific Cat K 680 FAST probe was tested in addition to the multicathepsin imaging agent VM249." (PMID 22437667, 2012).
schizophrenia (2 papers, 2011 to 2020). A major psychotic disorder characterized by abnormalities in the perception or expression of reality. "Up-regulation of cathepsin K expression in rats was directly linked to schizophrenia induced by treatment with neuroleptics." (PMID 21794126, 2011). "Cathepsin K has been recently detected in brain parenchyma and it has been linked to neurobehavioral disorders such as schizophrenia." (PMID 21794126, 2011). "On the other hand, an upregulation of CTSK seems to be associated with schizophrenia." (PMID 32793006, 2020). "An analysis of post mortem brains of individuals with schizophrenia has identified an upregulation of CTSK expression, compared to matched controls." (PMID 32793006, 2020). "Interestingly, post-mortem brain tissue from patients with schizophrenia also revealed an increase in the cathepsin K protein levels." (PMID 21794126, 2011).
tongue cancer (2 papers, 2013 to 2018). A malignant neoplasm affecting the tongue. "Instead, cathepsin K in the invasive TME front seems to have a protective role in the complex progression of tongue cancer." (PMID 23951042, 2013). "We wanted to verify the expression of cathepsin K mRNA and protein in tongue carcinoma HSC-3 cells cultured in two different types of 3D organotypic models." (PMID 23951042, 2013).
tongue SCC (2 papers, 2018 to 2023). "However, only one study exists in the literature regarding the prognostic value of CTSK in tongue SCC." (PMID 29618339, 2018).
type 1 diabetes (2 papers, 2017 to 2023). "Nevertheless, a detrimental role of CTSK in the diabetic heart has been demonstrated in streptozotocin-induced type 1 diabetes using CTSK knockout mice." (PMID 36742461, 2023).
type 2 diabetes (2 papers, 2017 to 2023). "A 7-year long follow-up study performed by the same authors concluded that serum CTSK levels in type 2 diabetes patients are indicative of vascular endothelial dysfunction and deterioration of renal function." (PMID 29123184, 2017).
aneurysmal disease (1 paper, 2013). "Changes in the macrophage polarization are paralleled by clear, but selective changes for markers such as cathepsin K and S, and ALOX5 which have been linked to macrophage differentiation as well as aneurysmal disease." (PMID 23349755, 2013).
apical periodontitis (1 paper, 2019). "Administration of cathepsin K inhibitor effectively downregulated apical periodontitis development and synthesis of proinflammatory cytokines." (PMID 31166414, 2019).
Arterial thrombosis (1 paper, 2024). The formation of a blood clot inside an artery. "Here we investigated the beneficial effects of genetic and pharmacological inhibitions targeting CTSK in stress-related arterial thrombosis in mice in response to FeCl3." (PMID 38703204, 2024).
asthma (1 paper, 2025). "Experimental studies demonstrated significantly increased Cathepsin K expression in airway epithelium correlating with airway remodelling severity in HDM-induced mouse asthma models." (PMID 41573715, 2025). "Given its known cardiovascular and cerebrovascular side effects, future development of asthma treatments targeting Cathepsin K must prioritise target specificity and systemic safety." (PMID 41573715, 2025).
bronchopulmonary dysplasia (1 paper, 2014). Bronchopulmonary dysplasia is a chronic respiratory disease that results from complications related to lung injury during the treatment of infant acute respiratory distress syndrome in low-birth-weight premature infants or from abnormal lung development in older infants. "Cathepsin K expression levels are significantly reduced in the lungs of premature infants with bronchopulmonary dysplasia; in contrast, cathepsin K is upregulated in fibrotic adult lungs, suggesting a protective role against excessive collagen deposition in adult chronically diseased lungs." (PMID 24743169, 2014).
cerebrovascular disease (1 paper, 2020). "The development of odanacatib, a cathepsin K inhibitor, was discontinued due to an apparent increase in the risk of cerebrovascular disease observed in the pivotal phase 3 study and an increase in the composite MACE endpoint in the phase 3 extension trial of odanacatib." (PMID 32658264, 2020).
chronic obstructive pulmonary disease (1 paper, 2023). A chronic and progressive lung disorder characterized by the loss of elasticity of the bronchial tree and the air sacs, destruction of the air sacs wall, thickening of the bronchial wall, and mucous accumulation in the bronchial tree. "Importantly, cathepsin K–mediated phagosomal collagenolysis in lung RTMs is negatively regulated by fibrosis-related stimuli and reduced in macrophages from chronic obstructive pulmonary disease (COPD) patients." (PMID 36697252, 2023).
cutaneous squamous cell carcinoma (1 paper, 2023). "CD200 expression reportedly plays a prometastatic role in cutaneous squamous cell carcinoma (cSCC), and metastasis was induced through upregulation of the cysteine protease cathepsin K (Ctsk) in CD200-positive cSCC." (PMID 37894750, 2023).
dermatofibroma (1 paper, 2025). "DFSP stains positive for CD34 and vimentin and negative for S100, factor XIIIa, podoplanin D2-40, stromelysin III, and cathepsin K. This helps differentiate DFSP from benign entities such as dermatofibroma." (PMID 41393578, 2025).
emphysema (1 paper, 2024). "CTSK is partially responsible for the loss of lung elasticity and recoil observed during the development of emphysema." (PMID 38612871, 2024). "CTSK is up-regulated in alveolar macrophages of emphysema patients and in the lungs of cigarette smoke-exposed guinea pigs." (PMID 38612871, 2024).
endometriosis (1 paper, 2025). The growth of functional endometrial tissue in anatomic sites outside the uterine body. "On the other hand, as a candidate diagnostic biomarker, CTSK has been depicted as one of the players in inflammation-related pathways in recent studies involving women with endometriosis." (PMID 41374450, 2025).
eosinophilia (1 paper, 2023). "Although we could not find a relevant literature report, our mediation analysis suggested that CTSK expression might have a causal effect on NP through eosinophilia." (PMID 37424726, 2023).
hepatocellular carcinoma (1 paper, 2024). A malignant tumor that arises from hepatocytes. "Research on hepatocellular carcinoma (HCC) revealed that CTSK significantly influences cell proliferation." (PMID 39559351, 2024). "Several recent studies have shown a strong correlation between increased CTSK levels and the onset and poor prognosis of pancreatic and hepatocellular carcinomas." (PMID 39559351, 2024).
HIV-1 infection (1 paper, 2015). The type species of lentivirus and the etiologic agent of acquired immunodeficiency syndrome (AIDS). "Furthermore, HIV-1 infection induced formation of larger osteoclastst, enhanced the expression of mRNAs for three osteoclast specific marker molecules (tartrate-resistant acid phosphatase, cathepsin K, and the calcitonin receptor), and up-regulated osteoclast bone resorption activity." (PMID 25809599, 2015).
Hyperglycemia (1 paper, 2017). An increased concentration of glucose in the blood. "However, in both these models, it is uncertain whether cathepsin K knockout has a direct effect on cardiac anomalies associated with overt hyperglycemia as the former is a model for insulin resistance whereas the latter is a model for pressure-overload." (PMID 28821796, 2017).
Hypertension (1 paper, 2025). The presence of chronic increased pressure in the systemic arterial system. "Overexpression of Cathepsin K in kidney mesangial cells indirectly increases peroxisome proliferator-activated receptor-gamma-caspase-8-mediated cell apoptosis, kidney remodelling and hypertension." (PMID 41325840, 2025).
invasive carcinoma (1 paper, 2013). A carcinoma that is not confined to the epithelium, and has spread to the surrounding stroma. "The reasons for the variable expression of cathepsin K in the invasive carcinoma cells and tumor front of the TME and its seemingly complementary relationship in vitro can obviously be due to the more complex regulation and interaction of cells in cancer." (PMID 23951042, 2013).
invasive ductal carcinoma of the (1 paper, 2018). "Overexpression of CTSK has been observed in invasive ductal carcinoma of the breast, lung and prostate adenocarcinoma." (PMID 29618339, 2018).
ischemia (1 paper, 2021). A hypoperfusion of the BLOOD through an organ or tissue caused by a PATHOLOGIC CONSTRICTION or obstruction of its BLOOD VESSELS, or an absence of BLOOD CIRCULATION. "In contrast to the control group (10% FBS treatment alone), the serum insufficiency (0.1% FBS) and ischemia groups did not exhibit increases in CTSK or NFATc1 expression; only RANKL stimulation increased the expression levels of both proteins." (PMID 34204469, 2021).
male reproductive system diseases (1 paper, 2023). "Utilizing the CTD database, we demonstrated that the five hub genes (CD300LB, CMKLR1, CCR4, B3GALT5, and CTSK) significantly affected male reproductive system diseases." (PMID 37152990, 2023).
memory impairment (1 paper, 2016). "In particular, cathepsin K deficient mice exhibited marked memory impairments in behavioral assessments, as indicated by their inability to discriminate the introduction of a novel object into a familiar environment." (PMID 27375486, 2016).
myositis (1 paper, 2024). "In terms of myositis, marker genes encoding lysosomal proteins including cathepsins (CTSA, CTSK), IFI30 Lysosomal Thiol Reductase (IFI30) and CD74 Molecule (CD74) suggested active lysosome and immune cells activities in muscle turnover." (PMID 38342952, 2024).
ocular hypertension (1 paper, 2021). Abnormally high intraocular pressure. "We found that CTSK expression is tightly regulated by mechanical stress, as well as in response to ocular hypertension inducing factors, including DEX, TGFβ2, Endo-1, and CTGF." (PMID 34831087, 2021).
oral diseases (1 paper, 2025). "As GCF may be recognized as a new source of diagnostic and prognostic biomarkers of oral diseases, this finding further supports the critical role of CTSK in the pathological process of OTM gingival recession." (PMID 40315697, 2025).